ENSG00000277945 (novel transcript, sense intronic to HMGA2)
Gene: Long non-coding RNA gene on chromosome 12 (65,830,750 to 65,831,050, forward strand). Ensembl gene ENSG00000277945.
Gene Ontology:
Molecular function: ubiquitin-like ligase-substrate adaptor activity
Biological process: negative regulation of ferroptosis; positive regulation of proteasomal ubiquitin-dependent protein catabolic process
Cellular component: cytosol